RN7SKP81 (RN7SK pseudogene 81)
Gene: Miscellaneous RNA gene on chromosome X (143,090,347 to 143,090,677, forward strand). Ensembl gene ENSG00000202473.
Homologues: Orthologues: chimpanzee 7SK (99% identical), mouse Gm56340 (55% identical). Paralogues in human: 7SK (77% identical), RN7SKP118 (76% identical), RN7SKP187 (76% identical), RN7SKP48 (73% identical), RN7SKP174 (73% identical), RN7SKP227 (72% identical), RN7SKP185 (72% identical), RN7SKP62 (72% identical), RN7SKP55 (70% identical), RN7SKP76 (70% identical), RN7SKP292 (69% identical), RN7SKP178 (69% identical), and 284 more.